LINC02228 (long independently transcribed non-coding RNA 2228)
Synonyms: HIKER
Gene: Long non-coding RNA gene on chromosome 5 (25,048,811 to 25,190,956, reverse strand). Ensembl gene ENSG00000251273.
Diseases named in the same sentence as LINC02228 in open-access papers:
LINC02228 is named in the same sentence as 1 disease in open-access papers, as found by Europe PMC text mining. Sharing a sentence is not in itself a finding about the gene and the disease. The quoted sentences say what the papers report.
Monge’s disease (1 paper, 2023). "In summary, our study identified a group of lncRNAs and delineated the critical role of HIKER/LINC02228 in the EE of Monge’s disease." (PMID 37022795, 2023). "We also prove, for what we believe is the first time, that the lncRNA HIKER/LINC02228 regulates the excessive erythropoiesis of Monge’s disease and that its action is mediated through CSNK2B, a casein kinase." (PMID 37022795, 2023).